GVINP1 (GTPase, very large interferon inducible pseudogene 1)
Synonyms: GVIN1; VLIG1; VLIG-1; FLJ13373; GVIN1P
Gene: Transcribed unitary pseudogene on chromosome 11 (6,714,610 to 6,721,880, reverse strand). Ensembl gene ENSG00000254838.
Subcellular location: Cytoplasm, cytosol; Nucleus
Diseases named in the same sentence as GVINP1 in open-access papers:
GVINP1 is named in the same sentence as 16 diseases in open-access papers, as found by Europe PMC text mining. Sharing a sentence is not in itself a finding about the gene and the disease. The quoted sentences say what the papers report.
lung adenocarcinoma (2 papers, 2020 to 2025). A carcinoma that arises from the lung and is characterized by the presence of malignant glandular epithelial cells. "The lncRNA GVINP1 can bind with guanosine triphosphate selectively and noncovalently, and it has been found to be an independent prognostic marker for lung adenocarcinoma (LUAD) and NSCLC patients." (PMID 33329695, 2020). "GVINP1 selectively and non-covalently binds to guanosine triphosphate (GTP) and has been identified as an independent prognostic marker for patients with lung adenocarcinoma (LUAD) and non-small cell lung cancer (NSCLC)." (PMID 40282343, 2025).
breast carcinoma (1 paper, 2022). "We constructed a novel 6-gene signature (SQSTM1, GDF9, LINC01125, PTGS2, GVINP1, and TMEM64) and used an XGBoost model to predict the metastatic status in breast cancer (AUC = 0.82)." (PMID 35436939, 2022). "In conclusion, our present research constructed a novel 6-gene signature (SQSTM1, GDF9, LINC01125, PTGS2, GVINP1, and TMEM64) by feature importance score and used an XGBoost model to predict the metastatic status in breast cancer (AUC = 0.82, higher than the previous studies to our knowledge)." (PMID 35436939, 2022). "We speculated whether these 5 genes, LINC01125, GDF9, PTGS2, GVINP1, and TMEM64, contributed to breast cancer metastasis because of immune dysfunction and conducted an exploration from the immune cell perspective." (PMID 35436939, 2022). "Researches on gene LINC01125, gene GDF9 and gene GVINP1 is very limited, no studies have shown that there is a link between gene TMEM64 and breast cancer." (PMID 35436939, 2022).
breast tumor (1 paper, 2022). "To elucidate the biological functions of SQSTM1, GDF9, LINC01125, PTGS2, GVINP1, and TMEM64 in breast tumor cells, we knocked down the expression of the 6-gene signature using shRNA or the negative control in MCF-7 cell lines to assess cell proliferation, migration and invasion in vitro." (PMID 35436939, 2022).
lung carcinoma (1 paper, 2022). "GVINP1 was downregulated in lung cancer and related to poor prognosis of patients with lung cancer." (PMID 36272991, 2022).
melanoma (1 paper, 2023). A malignant, usually aggressive tumor composed of atypical, neoplastic melanocytes. "It is thus intriguing that GVINP1 predicts resistance to ICB therapy in melanoma and other cancer as a single gene and a component gene of corrB2." (PMID 36588164, 2023).
skin cancer (1 paper, 2020). "In addition to the mutations in genes known to be associated with skin cancer development, we identified multiple new UV target genes that harbor high frequency of T > C conversions, including GVINP1, NCF1B, FLG2, and SPEF2." (PMID 32188867, 2020).
tumor (2 papers, 2022). "In general, the effects of SQSTM in tumor cells are assigned as a risk factor, while the effects of the other 5 genes (GDF9, LINC01125, PTGS2, GVINP1, and TMEM64) in immune cells are assigned as protective factors." (PMID 35436939, 2022). "In summary, we assigned the effects of SQSTM in tumor cells as a risk factor and the effects of other 5 genes (GDF9, LINC01125, PTGS2, GVINP1, and TMEM64) in immune cells as protective factors." (PMID 35436939, 2022). "Except for GVINP1 and NCF1C, the expression of the other 5 prognosis-related DE pseudogenes (DDX12P, FER1L4, NSUN5P2, PLEKHA8P1 and RP9P) were higher in tumor tissues than in cutting edge normal tissues, which was totally consistent with the results of TCGA samples." (PMID 36272991, 2022).
GVINP1 also shares sentences with these, for which no sentence is quoted: infection (7 papers); viral infection (3); bacterial infection (1); cancer (1); cardiovascular disease (1); immune dysfunction (1); infectious disease (1); Obesity (1); pancreatic cancer (1).